MMP13 (matrix metallopeptidase 13)
Diseases named in the same sentence as MMP13 in open-access papers (continued):
Sharing a sentence is not in itself a finding about the gene and the disease.
osteoarthritis (continued). "This aligns with previous work describing a decreasing GAG production along with higher MMP13 production and type X collagen synthesis, along with hypertrophic chondrocyte differentiation in fracture callus, in osteoarthritis-related hypertrophy, or during development." (PMID 41294826, 2025). "In oestrogen-deficient rats with osteoarthritis induced by monosodium iodoacetate (MIA), MP also preserved joint integrity by modulating the expression of matrix metalloproteinase-13 (MMP-13) and its inhibitor, i.e., Tissue Inhibitor of Metalloproteinase-3 (TIMP-3)." (PMID 40649931, 2025). "In contrast, plasma MMP-13 and CS, although recognized as biomarkers associated with osteoarthritis, did not change significantly after IV HA treatment." (PMID 41227470, 2025). "Additionally, acetyl-CoA orchestrates epigenetic modulation, affecting multiple cellular processes critical for osteoarthritis pathogenesis, including the transcriptional activation of MMP13 and ADAMTS7." (PMID 40425566, 2025). "Finally, sulphonamide 4 is a lead compound for the treatment of osteoarthritis via MMP-13 (matrix metalloproteinase 13) inhibition which exhibited an excellent selectivity profile and complete inhibition of collagenolysis in vitro." (PMID 40589432, 2025). "Genes associated with osteoarthritis, DDH, and FAI include COL1A1, MMP13, and IL-6." (PMID 41019141, 2025). "Moreover, recent studies have further revealed the extensive roles of miRNAs in osteoarthritis, particularly in crucial pathways such as MMP13, STAT3, SMAD2/3, NOTCH3/Notch, and NF-κB signaling." (PMID 39796139, 2024). "Similarly, it has been demonstrated to improve osteoarthritis by inhibiting the secretion of matrix metallopeptidase 13 (MMP-13) through the relative expression of the nuclear factor kappa-B ligand (RANKL)/osteoprotegerin (OPG) ratio." (PMID 39459639, 2024). "Similarly, ginsenoside Rg1 was found to improve osteoarthritis symptoms by alleviating cartilage degradation and reducing MMP-13 in a rat model of osteoarthritis generated through anterior cruciate ligament transection (ACLT)." (PMID 38892015, 2024). "Sleep deprivation could activate the p-ERK pathway in rat mandibular condylar chondrocytes, increases the expression of matrix-degrading enzymes MMP1, MMP3, and MMP13, and leads to osteoarthritis-like lesions in the temporomandibular joint." (PMID 39010104, 2024). "Moreover, their study found that MMP-13 levels in RA synovial fluid are significantly higher than those in patients with osteoarthritis (OA), making MMP-13 a useful marker for distinguishing between RA and OA in diagnostic evaluations." (PMID 39430588, 2024). "An increase in the level of MMP-13 in synovial fluid is important in the development and progression of osteoarthritis, even if the expression of MMP-13 in the cartilage itself does not change or only changes slightly in the early stages of development, while the mRNA levels of MMP-13 are increased." (PMID 38396667, 2024). "Future research will focus on analyzing the protein expression of MMP-2, MMP-3, MMP-9, and MMP-13 to more fully elucidate the molecular mechanisms by which BSRE impacts osteoarthritis progression, providing valuable insights for developing more effective therapeutic strategies." (PMID 38542192, 2024). "β-cryptoxanthin, though less studied, has been shown to decrease the expression of inflammatory cytokines (IL-1β, TNF-α, and IL-6) and matrix metalloproteinase 13 (MMP-13) in the primary chondrocytes of mice, leading to amelioration of osteoarthritis development." (PMID 39201397, 2024). "Indeed, studies have identified NF-κB as abnormally activated in osteoarthritis, and several studies have demonstrated that the increase in MMP-13 expression after IL-1β was dependent of the activation of this transcription factor." (PMID 38543230, 2024).
osteoarthritis (continued). "In addition, EA can inhibit the expression of MMP13 in an osteoarthritis model, thereby reducing the expression of related inflammatory factors in the osteoarthritis model." (PMID 37831322, 2023). "In addition, a recent study found that PKR activation induced by TNF-α also plays an important role in the pathogenesis of osteoarthritis, triggering oxidative stress-mediated inflammation and MMP-13 in chondrocytes." (PMID 36838594, 2023). "In addition, one study revealed that lncRNA TUG1 governed ECM degradation of chondrocytes in osteoarthritis via control of miR-320c/MMP-13 pathway." (PMID 37779916, 2023). "Furthermore, knockdown of SND1 expression inhibited MMP13 and promoted collagen II protein expression in osteoarthritis rat knee joint cartilage tissues." (PMID 37749650, 2023). "Interestingly, a previous study has shown that AREG interacts with EGFR, activating PI3K/Akt, and subsequently inducing the NF-κB transcription factor interaction with the MMP-13 promoter, inducing cartilage destruction in osteoarthritis." (PMID 35841013, 2022). "Thus MMP-13 has an essential role in the progression of human carcinoma and metastatic processes, the development of acute articular rheumatism, and osteoarthritis." (PMID 35163727, 2022). "However, HIF-1 inhibits the Wnt/β-catenin signaling pathway in osteoarthritis and lowers MMP13 to reduce catabolic activity." (PMID 36232501, 2022). "A previous study demonstrated that dexamethasone had a chondroprotective effect, that is, it ameliorated arthritic pain and protected cartilage from damage in a rabbit osteoarthritis model via suppressing several pro-inflammatory gene markers, including il-1b, il-8, il-6, tnf-α, mmp-3, and mmp-13." (PMID 36429168, 2022). "MMP13 is considered the key enzyme of cartilage degradation in osteoarthritis." (PMID 35449811, 2022). "As such, MMP-13 is overexpressed in the cartilaginous tissues of patients with osteoarthritis, and an increased level of MMP-13 in chondrocytes may be an initial mechanism in the development of osteoarthritis." (PMID 35163727, 2022). "Meanwhile, Runx2 conditional knockout mice showed biphasic phenotypes: heterozygous knockout inhibited osteoarthritis and decreased matrix metallopeptidase 13 (Mmp13) expression, while homozygous knockout of Runx2 accelerated osteoarthritis and reduced type II collagen (Col2a1) expression." (PMID 36261443, 2022). "MicroRNA-222 and microRNA-27b regulate MMP13 expression in osteoarthritis chondrocytes." (PMID 33920915, 2021). "MMP-13 levels in patients with osteoarthritis indicate the degree of cartilage degeneration." (PMID 33461534, 2021). "In support of this notion, in 6-month old Wnt9a∆Prx/− specimens ADAMTS5- and MMP13-positive cells were observed in the synovium, and 9-month and older Wnt9a∆Prx/− mice develop osteoarthritis-like changes in their joints (C.H. and S.T. manuscript in preparation)." (PMID 33990546, 2021). "Alteration of the osteoarthritis pathway due to RARγ agonist treatment was associated with the up-regulation of catabolic genes (ADAMTS5, HES1, and MMP13), inhibition of cartilage matrix anabolic genes (COL2A1, ACAN, and SOX9) and the up-regulation of death genes (CASP4)." (PMID 32294904, 2020). "Furthermore, several studies have investigated the MMP-13 level in osteoarthritis patients, and consistent observation is obtained, whereby the MMP-13 level increased significantly in patients with osteoarthritis." (PMID 32189997, 2020). "Additionally, C/EBPβ can reportedly induce expression of MMP13, a major collagenase for type 2 collagen, in cooperation with Runx2, consequently promoting osteoarthritis." (PMID 32079226, 2020). "Furthermore, TUG1 is associated with poor prognosis for osteoarthritis patients, and the elevated expression of this lncRNA promotes osteoarthritis-induced degradation of chondrocyte extracellular matrix via the miR-195/MMP-13 axis." (PMID 32791451, 2020).
osteoarthritis (continued). "The findings suggested that introduction of miR-448 significantly decreased the protein expression of matrilin-3 and the mRNA levels of aggrecan and type II collagen, and enhanced the secreted protein expression of MMP-13 compared with osteoarthritis chondrocytes transfected with miR-NC." (PMID 29483929, 2018). "MMP-13 is a major collagenase involved in the catabolic processes in osteoarthritis." (PMID 29483929, 2018). "It has been reported that interleukin-1 beta (IL-1β), one of the main cytokines involved in the pathogenesis of osteoarthritis, can inhibit cell proliferation, reduce the synthesis of aggrecan and type II collagen, and increase the expression of MMP-13 in chondrocytes." (PMID 29483929, 2018). "Additionally, geniposide markedly suppressed the expression of IL-1, TNF-α, NO, and MMP-13 in the synovial fluid from the rabbits with osteoarthritis." (PMID 29682561, 2018). "OPN promotes expression of MMP-13 through NF-κB signaling in osteoarthritis." (PMID 28505114, 2017). "MMP-13 not only is an enzyme responsible for bone resorption and cartilage destruction in rheumatoid arthritis and osteoarthritis, but also can degrade fibrillar type collagens, gelatin, basement membrane type IV collagen, fibronectin, tenascin, and proteoglycans." (PMID 29054963, 2017). "Conversely and for reasons that are not yet completely understood, pharmacological antagonism of the proinflammatory transmembrane protein Toll-like receptor 4 (TLR-4) results in heightened MMP-13 expression and a corresponding dramatic increase in the severity of osteoarthritis." (PMID 27478294, 2016). "MMP-13 is by far the most studied of the matrix metalloproteinases in terms of its role in cartilage, as it is considered the major catabolic effector in osteoarthritis and other forms of arthritis, owing to its robust ability to cleave the type II collagen that predominates in articular cartilage." (PMID 27478294, 2016). "While hyperinsulinemia is implicated in the chondrocyte apoptosis facet of osteoarthritis, expression of MMP-13 has not been documented to occur until the point of insulin resistance in the joint capsule." (PMID 27478294, 2016). "MiR-127 is an important regulator of MMP-13 in human chondrocytes and may contribute to the development of osteoarthritis." (PMID 26715101, 2015). "HtrA1, Ddr-2, and Mmp-13 are reliable biomarkers for osteoarthritis (OA), yet the exact mechanism for the upregulation of HtrA-1 is unknown." (PMID 23755017, 2013). "In addition, blocking LRP-5 expression in osteoarthritic chondrocytes resulted in a significant decrease in MMP-13 expression, the basic catabolic enzyme of osteoarthritis." (PMID 22513174, 2012). "In particular, the MMP-1 and MMP-13 collagenases play dominant roles in RA and osteoarthritis." (PMID 20804602, 2010). "In addition, MMP1 and MMP13 collagenases play dominant roles in RA and osteoarthritis because they are the rate-limiting components of the collagen degradation process." (PMID 19327174, 2009). "Mechanistically, these anti-osteoarthritis effects were associated with upregulated expression of COL2A1 and aggrecan in the articular cartilage, along with a decrease in inflammatory mediators (NO, PGE2), cytokines (IL-6, IL-1, TNFα), and cartilage-degrading enzymes (MMP-3 and MMP-13) in serum." (PMID 39519204, 2024). "Finally, combined with the OARSI score of osteoarthritis, we can find that rapamycin can indeed reduce the expression of cartilage damage-related factor MMP13, protecting Col2 in cartilage tissue from catabolism factor-induced degradation, thereby delaying the progression of PTOA in ACLT rats." (PMID 36120586, 2022). "The dysregulation of Hh signalling can lead to osteoarthritis, which is characterized by progressive degeneration of articular cartilage, and in Ihh‐depleted mice, the expression of osteoarthritis‐related markers, including MMP‐13 and collagen type X, was significantly down‐regulated." (PMID 34918401, 2022).
osteoarthritis (continued). "But in osteoarthritis, quiescent chondrocytes become activated and undergo proliferation and hypertrophic differentiation, characterized by enlarged cell size, enhanced expression of collagen type X, and upregulated expression of proteolytic enzymes, such as matrix metalloproteinase 13 (MMP13)." (PMID 35280506, 2022). "In addition, MMP-13 in the de novo tissues of the hUCB-MSC and rBM-MSC groups was much higher than that of the normal group, suggesting that the de novo tissues had the risk of osteoarthritis." (PMID 33708990, 2021). "Furthermore, increase IL-6 and MMP-13 level have been reported in osteoarthritis." (PMID 32886713, 2020). "In addition, the mRNA levels of typical aging markers (e.g., P16 and P21) and inflammation factors (e.g., IL6 and matrix metalloproteinase 13 (MMP13)) that are often upregulated in osteoarthritis were diminished in the articular cavities of the mice with DR8-WT or DR8-mtDRBD." (PMID 31350386, 2019). "Furthermore, enhanced levels of TGF-β could stimulate MMP13 expression in osteoblasts in vitro and TGF-β-stimulated MMP13 expression seemed to be involved in the pathogenesis of osteoarthritis." (PMID 31831031, 2019). "Moreover, it has been shown that Bortezomib prevents the degradation of collagen type II and the induction of MMP13 in vitro, thereby suggesting that it may have therapeutic effects in the context of osteoarthritis." (PMID 31351471, 2019). "Our study demonstrated that Circ_0136474 and MMP‐13 suppressed cell proliferation, while enhanced cell apoptosis by competitive binding to miR‐127‐5p in OA, which may well provide us with a new therapeutic strategy for osteoarthritis." (PMID 31402547, 2019). "Furthermore, TRAFD1 is suggested to induce inflammatory expression of MMP13 in osteoarthritis." (PMID 29931419, 2018). "Thus, drugs that inhibit Mmp13 expression may be possible therapeutic agents for osteoarthritis or arthritis diseases." (PMID 26582142, 2015). "Osteoarthritis (OA) is characterized by the accumulation of chondrocytes expressing p16INK4a and markers of the senescence-associated secretory phenotype (SASP), including the matrix remodeling metalloproteases MMP1/MMP13 and pro-inflammatory cytokines interleukin-8 (IL-8) and IL-6." (PMID 24572376, 2014). "However, during osteoarthritis, chondrocytes lose the stable phenotype and undergo changes that occur in terminal differentiated growth-plate chondrocytes, such as high expression of MMP-13 and collagen X." (PMID 22513174, 2012). "Interestingly, MMP-1 (or collagenase-1) and/or MMP-13 (or collagenase-3) are among the enzymes expressed by human chondrocytes in degenerative pathologies of cartilage, namely osteoarthritis and rheumatoid arthritis and are thus thought to play a critical role in cartilage destruction." (PMID 20193091, 2010). "During EMT, Matrix Metallopeptidase 13 (MMP13), a key regulator of chondrocyte senescence in Osteoarthritis (OA), is upregulated, contributing to PC metastasis." (PMID 41522514, 2026). "The reduced expression of interleukin-1β (IL-1β) upregulates the expression of MMP13 and COL10A1 genes, thereby mitigating the inflammatory response in osteoarthritis (OA)." (PMID 39857301, 2025). "Rg1 (10 μg/mL) treatment for 24 h suppressed IL-1β-induced mRNA expression of MMP-13 and COX-2 by 7.5- and 2.2-fold, respectively, in human chondrocytes from osteoarthritis patients with knee replacement." (PMID 40507179, 2025). "Owing to the key role of MMP13 and MMP3 in osteoarthritis, these two genes were of significant interest." (PMID 40583170, 2025). "Chlorogenic acid reversed the reduction in collagen II and the increase in iNOS/NO, IL-6, MMP-13, and COX-2/PGE2 levels in IL-1β-induced human SW-1353 chondrocytes, an in vitro model of osteoarthritis." (PMID 41515347, 2025).
osteoarthritis (continued). "RNA sequencing unveiled significant transcriptome changes during the 7-day SMG culture, including the notable upregulation of key osteoarthritis markers such as COL10A1, MMP13, and SPP1, along with pathways related to inflammation and calcification." (PMID 38907358, 2024). "MMP13 (collagenase-3) orchestrates bone formation and remodeling, and is the primary MMP involved in cartilage degradation in osteoarthritis." (PMID 38255947, 2024). "High expression levels of MMP3, MMP13, and ADAMT4 in articular cartilage of osteoarthritis signify excessive extracellular matrix degradation, thereby accelerating the course of osteoarthritis." (PMID 39840130, 2024). "Inhibition of MMP13 by CL82198 effectively reduced the degradation of type II collagen and reduced the number of osteoarthritis-related lesions." (PMID 38774874, 2024). "In osteoarthritis (OA) synovial cells stimulated by visfatin and resistin, an increase in MMP-1 and MMP-13 expression, along with a decrease in Col2a1 expression, has been observed." (PMID 39409194, 2024). "Increased expression of β-CATENIN has been found to directly increase the expression of MMP13, ADAMTS4, and ADAMTS5, ultimately leading to the degradation of joint cartilage matrix and the occurrence of osteoarthritis lesions." (PMID 39010104, 2024). "In a mouse model of posttraumatic osteoarthritis, curcumin has been found to slow the progression of osteoarthritis and relieve its symptoms by reducing the levels of MMP-1, MMP-3, MMP-13, ADAMTS5, IL-1β, and TNF-α." (PMID 37938371, 2024). "The analysis revealed a notable upregulation of key osteoarthritis markers, such as COL10A1, MMP13, and SPP1, along with downregulating chondrogenic markers, including ACAN, COL1A2, COL2A1, and SOX9." (PMID 39337501, 2024). "In knee osteoarthritis, administration of exogenous miR-17 downregulated the expression of pathological catabolic factors such as MMP13, ADAMTS5, and NOS2, thereby reducing extracellular matrix damage and alleviating the severity of osteoarthritis." (PMID 37016437, 2023). "Given the role of MMP13 as a major driver of osteoarthritis, we wanted to assess the role of MIA/CD-RAP-dependent MMP13 regulation under inflammation." (PMID 36672165, 2023). "Treatment of osteoarthritis with extracellular vesicles also reduced MMP activity and the expression of MMP-13, while the production of the anti-inflammatory cytokine IL-10 and the expression of col II was markedly increased." (PMID 36678850, 2023). "After establishing the DMM-induced osteoarthritis, we showed that the inhibition of PDK1 did promote OA progression by enhancing the expression of MMP13, accelerating the degradation of major ECM structural molecules, and promoting inflammatory responses." (PMID 37474941, 2023). "Meanwhile, we examined the osteoarthritis markers collagen type II (COL2A1) and matrix metalloproteinase 13 (MMP13)." (PMID 37620972, 2023). "Induction of an osteoarthritis-like phenotype in the ATDC5 chondrocytes was confirmed by a significant upregulation of il6, mmp13, and colx10a1 and a decrease in col2a1 and acan expression following treatment with IL-1β." (PMID 36814717, 2023). "As extracellular matrix proteins play a key role in the pathogenesis of osteoarthritis, it is indicated that ICS-CSSH promoted the synthesis and secretion of collagen II and inhibited the expression of MMP13, ADAMTS5." (PMID 36805735, 2023). "High concentrations of Mg2+ promote the synthesis of TIPM3 to further suppresses osteoarthritis by inhibiting the expression of ADAMTS4, ADAMTS5, and MMP-13." (PMID 36546928, 2022). "The inhibitory effect of Mg2+ on IL-1β, MMP13, and ADAMTS5 indicates that it has a certain potential in the treatment of osteoarthritis and 5–7.5 mM Mg2+ was most effective in inhibiting cartilage catabolism." (PMID 36546928, 2022).